IGFBP3 (insulin like growth factor binding protein 3)
Diseases named in the same sentence as IGFBP3 in open-access papers (continued):
Sharing a sentence is not in itself a finding about the gene and the disease.
Anxiety (5 papers, 2017 to 2023). Intense feelings of nervousness, tension, or panic often arise in response to interpersonal stresses. "These include sex, ethnicity, newborn LRRC34-rs10936600, maternal TL, paternal age, antenatal anxiety, plasma fasting glucose, and IGFBP3." (PMID 35073935, 2022). "Mothers with higher anxiety scores, elevated fasting blood glucose, lower plasma insulin-like growth factor-binding protein 3 and vitamin B12 levels, and active smoking status during pregnancy showed a higher risk of giving birth to offspring with shorter TL." (PMID 35073935, 2022). "The complexity and thus the computational burden of the full model forced us to remove total cholesterol, IGFBP3, and mothers’ state-anxiety from the full model." (PMID 34566794, 2021). "IGFBP-3 antagonism and IGF-I administration did not cause changes in the open arm entry percentage, a marker of anxiety." (PMID 28611445, 2017). "Negative correlations with baseline IL-1ra, IL-6, and IGFBP3 with changes in the BPRS-E manic and anxiety scores." (PMID 37763150, 2023).
Cerebral ischemia (5 papers, 2020 to 2022). Restriction of arterial blood supply to the brain associated with insufficient oxygenation to support the metabolic requirements of the tissue. "We identified Zfp580 as a novel factor that differentially modulates paracrine and endocrine Igf1 and Igfbp3 responses after cerebral ischemia." (PMID 35557964, 2022). "In order to further validate this finding, we also verified their expressional levels in patients with brain ischemia, and indeed showed that the level of Igfbp3 was increased and miR-185-5p decreased after brain ischemia in the blood of patients." (PMID 33262982, 2020). "The change in blood miR-185-5p and Igfbp3 expression is further confirmed in patients with brain ischemia." (PMID 33262982, 2020). "The changes of Igfbp3 and miR-185-5p after brain ischemia may represent early compensatory mechanisms for self-protection in the body." (PMID 33262982, 2020). "Furthermore, we verified the expressional changes of Igfbp3 and miR-185-5p in the serum of normal and patients with brain ischemia (BI)." (PMID 33262982, 2020). "In a rat model of cerebral ischemia/reperfusion injury miR-19a-3p was found to promote reperfusion-induced inflammation and apoptosis by downregulating IGFBP-3—implying a neuroprotective effect of IGFBP-3." (PMID 35597813, 2022).
chronic kidney disease (5 papers, 2012 to 2023). Impairment of the renal function secondary to chronic kidney damage persisting for three or more months. "Insulin-like growth factor I (IGF-I), which is mostly carried in blood by IGF-binding protein 3 (IGFBP-3), was associated to the glomerular filtration rate and chronic kidney disease in a multiethnic study among US adults." (PMID 23237568, 2012). "Moreover, multivariate analysis including age, sex, BMI, chronic kidney disease, BNP and insulin use (Model 2) revealed that an elevated IGF-1/IGFBP-3 ratio was associated with a significantly decreased risk for CV death and 3P-MACE." (PMID 35332212, 2022).
cognitive decline (5 papers, 2009 to 2023). "A separate study investigating insulin-like growth factors and cognitive function in the aging male population reported increased IGFBP3 was significantly associated with greater cognitive decline in their studied population." (PMID 37280551, 2023). "Current experimental studies and epidemiological findings on its relevance to AD were controversial, with some studies suggesting that higher serum total IGF-I levels and higher total IGF-I/IGFBP-3 ratios were associated with less cognitive decline." (PMID 36352898, 2022). "The bioinformatics data together indicate that upregulation of SERPINA1, VCP, PRNP, CIP2A, HSPA9, and UQCRC2 and downregulation of IGFBP3, CRHBP, PEPD, and GUSB were correlated to cognitive decline in T2DM patients." (PMID 36506101, 2022).
colitis (5 papers, 2019 to 2025). Inflammation of the colon. "Pharmacological blockade of IGFBP3/TMEM219 signal improves colitis in a T cell adoptive transfer model." (PMID 40371646, 2025). "The relevance of the IGFBP3/TMEM219 axis in reducing gut inflammation has also been confirmed in the IGFBP3–/– mice that were protected from DSS-mediated colitis." (PMID 40371646, 2025). "Colitis induction resulted in a significant reduction in GM-CSF, IGFBP-3, and both PDGF molecules compared to control mice." (PMID 36836678, 2023). "Parasitic infection during colitis was associated with elevated levels of AREG, EGF, IGFBP-3, and reduced levels of both PDGF-AA and -BB." (PMID 36836678, 2023). "The plasma IGFBP3 concentrations were significantly different among the three groups at d3 and d5 (F = 13.22, P < 0.001; F = 24.76, P < 0.001) and were significantly lower in both the colitis and pair-fed groups than those in the control group (P < 0.05)." (PMID 31221091, 2019). "Similarly, the chemopreventive effect of metformin has been previously demonstrated and the effects of IGFBP3 knockout and metformin were observed in a murine model of ulcerative colitis, showing significantly reduced colitis." (PMID 31480481, 2019). "However, IGFBP-3 was significantly increased when the parasite developed in mice with colitis." (PMID 36836678, 2023). "Overall, these results indicate that pharmacological blockade of the IGFBP3/TMEM219 signaling/binding with ecto-TMEM219 in vivo ameliorates signs and symptoms of acute colitis and preserves intestinal immune homeostasis." (PMID 40371646, 2025). "We also confirmed the effect of pharmacological blockade of the IGFBP3/TMEM219 signaling/binding in vivo in a DSS-induced acute colitis treatment approach, in which colitis was established first and administration of ecto-TMEM219 was then started at day +3." (PMID 40371646, 2025). "To strengthen our findings, we demonstrated in a proof-of-concept study that pharmacological blockade of the IGFBP3/TMEM219 signaling/binding with ecto-TMEM219 successfully improved the signs and symptoms of colitis in a T cell adoptive transfer model, which better parallels the pathogenesis of CD." (PMID 40371646, 2025). "Additionally, both decreased IGFBP3 and increased IGFBP2 levels were found in the colitis group, and the levels of two binding proteins were significantly correlated with calprotectin." (PMID 31221091, 2019). "To further test IGFBP3/TMEM219 blockade in a model that better mimics the chronic inflammation of CD, we used the DSS-mediated chronic colitis treatment model, in which colitis was induced with 3 cycles of oral DSS and ecto-TMEM219 was started after the colitis establishment at day +18." (PMID 40371646, 2025).
colonic carcinoma (5 papers, 2006 to 2022). "GH receptor antagonist treatment decreased colon carcinoma growth in nude mice, associated with reduction in circulating IGFBP3 levels." (PMID 17181856, 2006). "Other researchers reported that IGFBP-3 inhibited TNF-α-induced nuclear factor-kappa B activity in human colonic carcinoma cells." (PMID 23592916, 2013). "Additionally, 1,25-(OH)2D3 induces antiproliferative genes such as CEBPA (CCAAT-enhancer-binding protein-α) and IGFBP3 (insulin-like growth factor binding protein-3) in breast, prostate, or colon carcinoma cells, respectively." (PMID 35406059, 2022).
Crohn disease (5 papers, 2018 to 2025). A gastrointestinal disorder characterized by chronic inflammation involving all layers of the intestinal wall, noncaseating granulomas affecting the intestinal wall and regional lymph nodes, and transmural fibrosis. "Notably, the IGFBP1/IGFBP3 locus was recently associated by GWAS with poor prognosis in patients with Crohn’s disease, where IGFBPs have been suggested to play a role in both the inflammatory response and fibrosis." (PMID 35085231, 2022). "Circulating IGF-1 and IGFBP-3 are also decreased in patients with Crohn’s disease or in experimental colitis, where the inflammatory markers correlated with both proteins." (PMID 34502376, 2021). "The low bioavailability of IGFBP3 in protein losing enteropathy and Crohn’s disease partially explained the role of systemic inflammation in decreasing IGF-1 level." (PMID 29445110, 2018). "Upregulation of endogenous IGFBP3 and TGF-β1 expression enhances excess collagen IαI production in SMCs and contributes to fibrosis and stricture formation in Crohn's disease via a TGF-βRII/I-dependent and Smad2/3-dependent mechanism." (PMID 35154570, 2022). "Circulating IGFBP-3 seems to be less affected by undernutrition than IGF-1, since in Crohn’s disease patients, there is correlation between body mass index and IGF-1 but not with IGFBP-3." (PMID 34502376, 2021).
diabetic retinopathy (5 papers, 2012 to 2014). "Since IGFBP-3 is protective to the diabetic retina and TNFα is causative in the development of diabetic retinopathy, we wanted to better understand the cellular mechanisms by which TNFα can reduce IGFBP-3 levels." (PMID 25073020, 2014). "Our findings establish IGFBP-3 as a pivotal regulator of the insulin receptor/TNFα pathway and a potential therapeutic target for diabetic retinopathy." (PMID 24695399, 2014). "Since TNFα and IGFBP-3 are key mediators of retinal damage and protection respectively in diabetic retinopathy, increased understanding of the relationship between these two proteins will offer new therapeutic options for treatment." (PMID 25073020, 2014). "Our previous studies in retinas of diabetic rats have shown that Compound 49b, a novel β-adrenergic receptor agonist, prevented diabetic changes by increasing IGFBP-3 and decreasing TNFα, thus restoring insulin signaling and protection against diabetic retinopathy." (PMID 24695399, 2014). "The use of IGFBP-3 as an anti-inflammatory agent in this manner may offer alternate means for treating diabetic retinopathy." (PMID 23592916, 2013). "The inhibition of monocyte-REC adhesion by IGFBP-3 suggests that IGFBP-3 may have a role in regulating inflammation in diabetic retinopathy." (PMID 23592916, 2013). "Thus, we investigated IGFBP-3 actions on cell migration and adhesion invasive properties as they may relate to diabetic retinopathy." (PMID 23592916, 2013). "This response is IGF-1- and calcium-independent, but requires PI3K/Akt activation, suggesting that IGFBP-3 has novel protective effects on retinal and systemic vasculature and may be a therapeutic candidate for ocular complications such as diabetic retinopathy." (PMID 22792172, 2012). "We also confirmed an inhibitory effect of IGFBP-3 on monocyte adhesion to the REC monolayer, providing a new molecular mechanism of IGFBP-3 actions in cellular adhesion in diabetic retinopathy." (PMID 23592916, 2013). "The goal of this study was to characterize the effects of IGFBP-3 actions on REC-monocyte adhesion relevant in the progression of diabetic retinopathy, independent of any IGF-1 response." (PMID 23592916, 2013). "IGFBP-3 overexpression in the retinal endothelium has also been shown to restore vascular integrity, suggesting that IGFBP-3 may represent treatment of diabetic retinopathy." (PMID 23383064, 2013).
endometriosis (5 papers, 2022 to 2024). The growth of functional endometrial tissue in anatomic sites outside the uterine body. "Studies on the association between IGF‐1 and endometriosis were inconsistent, but according to a recent prospective study, IGF‐1 and IGFBP‐3 were associated with a higher risk of endometriosis among younger women." (PMID 36259314, 2022). "This miRNA has been shown to be downregulated in the ectopic endometrium of women and baboons with endometriosis, while IGFBP3 and COL8A1 expression was increased in the ectopic endometrial tissue." (PMID 38892003, 2024). "Increased expression of IGFBP3 in the glandular epithelial cells during the secretory phase was also confirmed in our baboon model of endometriosis." (PMID 37188982, 2023). "In contrast to the attenuation of miR-210 expression in EcE, RT-qPCR analysis revealed that the expression of IGFBP3 was significantly increased in EcE compared to EuE in women (P < 0.05) and baboons (P < 0.01) with endometriosis." (PMID 37188982, 2023). "IGFBP3 in endometriosis has been investigated in the peritoneal fluid (PF), and consequently expanded to the eutopic endometrium and endometriotic lesions previously only in human samples." (PMID 37188982, 2023). "The expression of IGFBP3 in the glandular epithelium was increased in EcE compared to EuE of women and baboons with endometriosis in the secretory phase." (PMID 37188982, 2023). "Another miRNA that plays a role in endometriosis is miR-210 and its targets IGFBP3 and COLA8A1." (PMID 38892003, 2024). "Previous microarray studies on gene expression profiles have shown that miR-210 and its downstream targets (IGFBP3 and COL8A1) play a role in pathophysiology of endometriosis, but the underlying mechanisms remain unclear." (PMID 37188982, 2023). "To identify the cell-specific localization of IGFBP3 and COL8A1 in vivo, we performed immunohistochemistry on matched mid-secretory EuE and EcE of women with endometriosis." (PMID 37188982, 2023). "To explore the characterization of IGFBP3 and COL8A1 in vivo, we performed RT-qPCR on matched mid-secretory EuE and EcE from baboons and women with endometriosis." (PMID 37188982, 2023).
Glucose intolerance (5 papers, 2017 to 2025). Glucose intolerance (GI) can be defined as dysglycemia that comprises both prediabetes and diabetes. "Animal experiments have shown that overexpression of human IGFBP-3 or its mutant devoid of IGF-binding ability leads to glucose intolerance with different effects on insulin secretion, insulin sensitivity, and lipid homeostasis in aging mice." (PMID 40027189, 2025). "The positive relationship between IGFBP-3 and lipid profiles in glucose intolerance state shown in the current study is consistent with the findings of reports about their metabolism." (PMID 34239560, 2021). "However, insulin-like growth factor binding protein (IGFBP) also plays an important role in glucose homeostasis, although the IGF-independent role of IGFBP-3 in the glucose intolerance state is poorly understood." (PMID 34239560, 2021). "Because serum IGF-I and total IGFBP-3 showed correlation with BMI, we examined whether serum IGF-I and total IGFBP-3 levels vary with BMI in subjects with glucose intolerance." (PMID 34239560, 2021).
ischemia (5 papers, 2015 to 2025). A hypoperfusion of the BLOOD through an organ or tissue caused by a PATHOLOGIC CONSTRICTION or obstruction of its BLOOD VESSELS, or an absence of BLOOD CIRCULATION. "Based on in vitro and in vivo analysis it was shown that miR-19a-3p directly targets and inhibits expression of IGFBP3, the gene encoding one of the insulin-like growth factors, and thus induce inflammation and apoptosis processes related to ischemia/reperfusion brain injury." (PMID 35562921, 2022). "Similarly, Igfbp3 expression was selectively induced in the ischemic hemisphere, while induction occurred earlier starting 24 h after ischemia and persisted up to 7 days." (PMID 35557964, 2022).
liver cirrhosis (5 papers, 2010 to 2024). "HCC was associated with lower serum IGF1 and IGFBP3 levels compared to liver cirrhosis (p = 0.037)." (PMID 29113370, 2017). "Then, rSVIGF1 therapeutic efficacy was studied in rats, in which liver cirrhosis was induced by carbon tetrachloride (CCl4) inhalation and showed that the hepatic levels of IGF1 and IGFBP3 were higher in rSVIGF1-treated rats than in control cirrhotic animals." (PMID 29702590, 2018). "IGFBP3 serum levels, such as IGF1, were related to severity of liver cirrhosis." (PMID 29702590, 2018). "IGFBP3 levels show significant negative correlation with α-fetoprotein (AFP) levels, with its cut-off value of <682.6 ng/mL discriminating between liver cirrhosis and HCC." (PMID 29702590, 2018).
lung disease (5 papers, 2012 to 2022). "The IGFBP3 pathway was involved in acute lung injury and ARDS in a proteomics study and in fibrotic lung disease in ARDS." (PMID 34573990, 2021). "Although SDC-1 and -4 have been implicated in fibrosis and have been suggested as targets for the treatment of lung diseases, we did not detect an increase of SDC-1, 3, or 4 in primary human fibroblasts in response to TGFβ or IGFBP-3." (PMID 22900087, 2012).
malnutrition (5 papers, 2015 to 2025). Inadequate nutrition resulting from poor diet, malabsorption, or abnormal nutrient distribution. "The present study used IGF-1 as a growth biomarker in stunting since it was more sensitive to nutritional deficiency than another biomarker, namely IGF Binding Protein 3 (IGFBP3)." (PMID 37946290, 2023). "Our study clearly demonstrated that serum IGF-1 and IGFBP-3 levels were dramatically lower in rats with malnutrition." (PMID 25909895, 2015). "Reduced hepatic IGF-1 and IGFBP-3 mRNA expression and serum protein levels observed in the rats with malnutrition in our study confirm the findings of previous studies." (PMID 25909895, 2015). "Malnutrition also has a strong inhibitory effect on IGF-I, IGFBP-3 and ALS, and serum concentrations are reduced by conditions that affect nutrition, such as coeliac disease and anorexia." (PMID 29724795, 2018). "IGF-I SDS and IGFBP-3 SDS below −2 would indicate an abnormality in the GH axis, provided that other factors, such as malnutrition, severe illness and trauma, have been eliminated." (PMID 29724795, 2018). "IGF-1 levels can be influenced by various factors, including age, pubertal stage, chronic illness, and malnutrition, while IGFBP-3 offers no significant advantage over IGF-1 in older children." (PMID 40598150, 2025).
preeclampsia (5 papers, 2014 to 2024). Preeclampsia is a hypertensive disorder of pregnancy that is characterized by new-onset hypertension with proteinuria presenting after 20 weeks of gestation, and depending on mild or severe forms may initially present with severe headache, visual disturbances, and hyperreflexia. "These include decidualization markers such as PRLR and IGFBP3, as well as genes that have previously been reported to have roles in trophoblast invasion, such as FERMT2 and RORB, for which expression changes in preeclampsia have been observed in fetal placenta." (PMID 39090334, 2024). "While several studies show a lack of a correlation between IGFI and/or IGFBP1 or IGFBP3 and preeclampsia, the majority report lower IGFI in women with preeclampsia." (PMID 27833901, 2016).
psoriasis (5 papers, 2023 to 2026). An autoimmune condition characterized by red, well-delineated plaques with silvery scales that are usually on the extensor surfaces and scalp. "Furthermore, IGFBP3 has been suggested as a factor contributing to epidermal hyper-proliferation in psoriasis." (PMID 38433211, 2024). "The levels of fasting glucose, insulin, IGFBP3, and IGFBP6 were higher in patients with psoriasis, while the levels of IGF-1, IGF-1R, and IGBP4 were higher in controls." (PMID 41635444, 2026). "IGFBP3 is a protease inhibitor in psoriasis, and changes in the IGF/IGFBP system may be involved in the pathogenesis of psoriasis." (PMID 37091865, 2023).